CX3CR1 (C-X3-C motif chemokine receptor 1)
Diseases named in the same sentence as CX3CR1 in open-access papers (continued):
Sharing a sentence is not in itself a finding about the gene and the disease.
asthma (continued). "In this study, analysis of the percentage of cells expressing CCR2 and CX3CR1 in the intermediate and non-classical monocyte subsets shows a strong inverse correlation, with CCR2 increased and CX3CR1 decreased, in patients with asthma compared to healthy controls." (PMID 31700522, 2019).
Cerebral ischemia (14 papers, 2014 to 2024). Restriction of arterial blood supply to the brain associated with insufficient oxygenation to support the metabolic requirements of the tissue. "In the context of brain ischemia, CX3CR1 deficiency exhibited beneficial effects due to the limited recruitment of Ly6Clow iNOS+ monocytes." (PMID 33411754, 2021). "In experimental models of spinal cord injury and focal cerebral ischemia, tissue damage is attenuated and function recovers earlier following injury in CX3CR1-deficient mice, effects attributed to reduced recruitment and/or activation of microglia/macrophages." (PMID 26329692, 2015). "The aim of this study was to investigate how CX3CR1 deficiency influences microglia/macrophage functions in the context of its protection following brain ischemia." (PMID 24490760, 2014). "Therefore, it appears that microglia/macrophage may play an important role in the regulation/modulation of the proinflammatory responses in cerebral ischemia, and their functions are attenuated by CX3CR1 deficiency." (PMID 24490760, 2014). "In the acute phase after cerebral ischemia, inhibition of CX3CR1 expression exacerbates ischemia-induced chronic cognitive impairment." (PMID 39206161, 2024). "Following cerebral ischemia, microglia expressing the fractalkine receptor (CX3CR1) are activated and drawn to the ischemic area." (PMID 37627275, 2023). "It was also found at elevated levels and associated with the protective immune milieu in the brain of Cx3cr1 KO mice following brain ischemia-reperfusion." (PMID 37771779, 2023). "Cx3cr1 was reported to be expressed in cultured neurons and induced in neurons and astrocytes following brain ischemia and severe seizures, respectively." (PMID 31201215, 2019). "We now report that CX3CR1 is upregulated in ischemic neurons in mice subjected to focal cerebral ischemia." (PMID 29323156, 2018). "For instance, in a model of cerebral ischemia and spinal cord injury, CX3CR1−/− mice showed neuroprotection and improved functional recovery." (PMID 26329692, 2015). "The work presented here provides important in vivo evidence for the role of the CX3CL1/CX3CR1 signaling pathway in the activation and neurotoxicity of microglia/ macrophage in cerebral ischemia." (PMID 24490760, 2014). "To date, little is known about the CX3CL1/CX3CR1 pathway in the context of microglia activation following brain ischemia." (PMID 24490760, 2014). "In summary, using a murine model of transient focal ischemia, we explored the consequences of CX3CR1 absence on microglia/macrophage proliferation/recruitment and on their activation after brain ischemia." (PMID 24490760, 2014). "Furthermore, there are also data postulating that the disruption of CX3CL1/CX3CR1 communication by the deletion of the cx3cr1 gene causes neurotoxicity in mouse models of systemic inflammation PD and ALS but protects against neuronal loss in a mouse model of focal cerebral ischemia." (PMID 35955430, 2022). "We hypothesized that CX3CR1 directly mediates brain ischemia-induced neuronal apoptosis." (PMID 29323156, 2018). "During cerebral ischemia, neurons release soluble CX3CL1, which reduces neuronal damage by binding to CX3CR1 in brain tissue and inhibiting microglia activation." (PMID 39206161, 2024). "In regards to acute CNS injury models (transient and permanent brain ischemia, spinal cord injury), the collective data suggest that the absence of CX3CR1 significantly reduces ischemic damage and inflammation." (PMID 24490760, 2014). "In the current study, using a murine model of transient middle cerebral artery occlusion (MCAO), we tested the consequences of the absence of CX3CR1 on microglia/macrophage proliferation/recruitment and on their neurotoxicity after brain ischemia." (PMID 24490760, 2014).
glomerulonephritis (14 papers, 2005 to 2026). A renal disorder characterized by damage in the glomeruli. "The effectiveness of immunotherapeutic inhibition targeting CX3CR1 has been demonstrated against glomerulonephritis associated with kidney diseases." (PMID 38951833, 2024). "The gut microbiota of Cx3cr1-deficient mice was corrected with Lactobacillus administration, and consequently, glomerulonephritis was reversed." (PMID 38299151, 2023). "Murine models of rapidly progressive glomerulonephritis have consistently demonstrated a pathophysiologic role of CX3CR1 and its ligand by using antibody blockade experiments and CX3CR1-deficient mice." (PMID 34009468, 2021). "Cx3cr1 deficiency exacerbated glomerulonephritis in MRL/lpr mice." (PMID 38299151, 2023). "CCR2+CX3CR1+ monocytes are preferentially recruited and acquire proinflammatory properties during glomerulonephritis." (PMID 38454505, 2024). "This suggests that CX3CR1 plays an important role in glomerulonephritis in MRL/lpr mice through a gut microbiota-dependent mechanism." (PMID 38299151, 2023). "Human expression data and experimental models consistently support a pathophysiologic role of CX3CL1/CX3CR1 in inflammatory processes in the renal cortex such as glomerulonephritis and transplant rejection." (PMID 34009468, 2021). "CX3CR1 expression is recognised as a mediator of disease severity in kidney disease, with immunotherapeutic inhibition of CX3CR1 shown effective against glomerulonephritis." (PMID 34765193, 2021). "Our findings contrast with the detrimental role of CX3CR1 in sterile inflammatory conditions such as atopic dermatitis, glomerulonephritis, and collagen-induced arthritis." (PMID 31316515, 2019). "In particular, the exclusive CX3CR1-dependent migration of kidney DCs promotes glomerulonephritis progression." (PMID 31316515, 2019). "An important role for the CX3CL1/CX3CR1 axis has also been demonstrated in renal diseases such as glomerulonephritis, tubulointerstitial nephritis, pyelonephritis, and renal allograft rejection." (PMID 24799766, 2014). "CX3CL1 expression recruits CX3CR1+ cells and prolong glomerulonephritis." (PMID 38299151, 2023). "Indeed the apical CX3CL1, firmly anchored to the membrane, facilitates recruitment and retention of the majority of CX3CR1+ leukocytes that infiltrate the kidney during glomerulonephritis or other nephropathies." (PMID 24799766, 2014). "CX3CR1/CX3CL1 axis is involved in the pathophysiology of inflammatory conditions such as cardiovascular disease, glomerulonephritis, and rheumatoid arthritis." (PMID 31316515, 2019). "While reports on ANCA-associated glomerulonephritis are lacking, both CX3CL1 and monocytes expressing CX3CR1 are known to be elevated in systemic lupus erythematosus." (PMID 34009468, 2021).
hepatocellular carcinoma (14 papers, 2019 to 2026). A malignant tumor that arises from hepatocytes. "Higher expression of CX3CL1/CX3CR1 correlates with better prognosis and fewer recurrences in hepatocellular carcinoma." (PMID 34316701, 2021). "For these reasons, increasing the expression of CX3CL1 and CX3CR1 in the tumor simultaneously improves the prognosis of patients with cancers such as colorectal cancer and hepatocellular carcinoma." (PMID 32466280, 2020). "With specific concern on HBV chronic infection, it was demonstrated that a differential expression of CX3CL1 produced by HBV-infected hepatocytes and hepatoma cells can affect the migration activity of CX3CR1+ immune cells, potentially contributing to the immunopathogenesis of HBV infection." (PMID 40733585, 2025). "In a study of hepatocellular carcinoma (HCC), scRNA-seq analysis not only highlighted an enrichment of CD8+ TEX in HCC, but also identified a CX3CR1 cluster of effector “memory-like” CD8+ T cells, drawing parallels to the findings in NSCLC." (PMID 31379821, 2019). "Spinal metastases in hepatocellular carcinoma patients also have high CX3CL1 and CX3CR1 expression, and CX3CL1 promoted hepatocellular carcinoma cell migration in vitro and spinal metastasis in vivo." (PMID 37025604, 2023). "In a model of hepatocellular carcinoma (HCC), HIF-1α upregulated the expression of chemokine (C-C motif) ligand 26 (CCL-26) in cancer cells, recruiting chemokine (C-X3-C motif) receptor 1 (CX3CR1) expressing-MDSCs to primary tumours and promoting HCC tumour growth." (PMID 31835751, 2019).
chronic kidney disease (13 papers, 2015 to 2025). Impairment of the renal function secondary to chronic kidney damage persisting for three or more months. "Systemic activation of CX3CL1/CX3CR1 contributes to chronic kidney disease-associated cardiovascular disease." (PMID 38299151, 2023). "In contrast, Cx3cr1 plays a protective role in a unilateral ureteral obstruction (UUO) model of chronic kidney disease although loss of Cx3cr1 once again reduced the number of kidney macrophages and dendritic cells." (PMID 37256130, 2023). "In this article we have highlighted a wealth of research from the past two decades that indicates a predominantly pathogenic role for the CX3CL1- CX3CR1 axis during both acute and chronic renal diseases." (PMID 34163473, 2021). "The present study highlights that SNP of CX3CR1 at V249M and T280M had a potential risk for end-stage renal diseases." (PMID 33986961, 2021). "CX3CR1 polymorphism may be involved in the pathogenesis of end-stage renal disease." (PMID 38299151, 2023). "CX3CR1 is a significant signal in the “AC finding” phase and plays a vital role in treating neuroinflammation and chronic kidney disease." (PMID 37886125, 2023). "As end-stage renal disease (ESRD) has been associated with a higher incidence of cardiovascular events and inflammation, the potential role of CX3CR1 polymorphisms, namely rs3732378 and rs3732379, has been suggested." (PMID 33672355, 2021). "It was reported that a single loss-of-function nucleotide polymorphism of CX3CR1 leads to exacerbation of chronic kidney disease compared to patients that do not have this loss of function." (PMID 38299151, 2023). "Loss of function of CX3CR1 leads to exacerbation of chronic kidney disease compared to patients that do not have this loss of function." (PMID 38299151, 2023). "The aortic CX3CL1/CX3CR1 axis is upregulated in chronic kidney disease in mice." (PMID 38299151, 2023). "Since the discovery of the chemokine fractalkine (CX3CL1) and its receptor, CX3CR1 over twenty years ago, a wealth of evidence has emerged linking CX3CL1-CX3CR1 signalling to renal pathologies in both acute and chronic kidney diseases (CKD)." (PMID 34163473, 2021). "In addition, in acute autoimmune kidney disease and in chronic kidney disease (CKD), CX3CR1 appears to be of major importance in the recruitment of immune cells and in the processes leading to macrophage-mediated fibrosis of the kidney." (PMID 34770776, 2021). "Plasma CX3CL1 was elevated in chronic kidney disease (CKD) patients and negatively correlated with estimated glomerular filtration rate (eGFR), suggesting a relationship between CKD and the CX3CL1/CX3CR1 axis." (PMID 40508161, 2025). "In a gene expression analysis of human monocytes, both, the non-classical monocyte marker CD16 and CX3CR1, were expressed at significantly higher levels on monocytes in patients with chronic kidney disease and cardiovascular events compared to all other groups." (PMID 34009468, 2021).
glioblastoma (13 papers, 2015 to 2026). The most malignant astrocytic tumor (WHO grade IV). "Of note, in a mouse model of glioblastoma, CX3CR1 deficiency led to increased CNS infiltration of CCR2+ monocytes into the tumor tissue, and it was suggested that this could be linked to increased microglial IL-1β, which in turn could induce CCL2 by tumor cells." (PMID 28320442, 2017). "Lastly, CX3CR1 expression was low among all CD4+ T-cell subsets except CD4+ Temra cells, where CX3CR1 expression was enriched in the blood and significantly lower in glioblastoma." (PMID 35464424, 2022). "While predominantly CX3CL1/CX3CR1 signalling is related to tumor progression, inactivation of the CX3CL1/CX3CR1 axis was shown to enhance glioblastoma development." (PMID 34988021, 2021). "In research on glioblastoma, inflammatory monocytes/macrophages have been revealed to express both CCR2 and CX3CR1, but microglia express only CX3CR1." (PMID 32849616, 2020). "Lastly, CX3CR1 expression was greatest in the blood for CD8+ Tem and Temra populations with a significant reduction in the frequency of CX3CR1+CD8+ Tem and Temra cells in glioblastoma samples." (PMID 35464424, 2022). "Similarly, we observed a decrease in the proportion of CX3CR1+CD4+ Temra and CX3CR1+CD8+ Tem and Temra subsets in glioblastoma compared to paired blood samples, suggesting little requirement for CX3CR1 in glioblastoma infiltration." (PMID 35464424, 2022).
systemic lupus erythematosus (13 papers, 2010 to 2025). An autoimmune multi-organ disease typically associated with vasculopathy and autoantibody production. "Through a CX3CR1-dependent mechanism, Lactobacillus spp. treatment attenuated splenomegaly and renal lymphadenopathy in murine lupus." (PMID 38299151, 2023). "To identify subcellular signature of CX3CR1+ macrophages in the lungs, we studied the change of the tissue-resident macrophage profile pattern in lupus mice with immunohistochemistry profile analysis." (PMID 37922035, 2023). "CX3CR1 and its ligand are highly regulated in human kidney diseases such as IgA nephritis, systemic lupus erythematosus, and inflammatory conditions such as transplant rejection." (PMID 34009468, 2021). "However, in a localized Imiquimod (IMQ)-induced lupus model, following the administration of P140, a significant accumulation of CX3CR1-positive macrophages was observed in the lungs of lupus-prone mice, along with the development of pulmonary fibrosis." (PMID 40055311, 2025). "Thus, based on the IMQ-induced lupus model, we found an intrinsic increase in IL-1R1 expression and extrinsic release of ROS in CX3CR1+ macrophages responses to P140 treatments." (PMID 37922035, 2023). "However, studies reported that an antagonist of CX3CL1 delayed the onset and slowed the progression of lupus nephritis in MRL/lpr mice, suggesting a detrimental role for CX3CL1/CX3CR1 interaction in lupus." (PMID 38299151, 2023). "A potential treatment of the leaky gut in lupus is to agonize CX3CR1 in antigen-presenting cells, which may activate these cells to clear any bacteria leaking from the gut." (PMID 38299151, 2023). "Thus, the results suggest P140-induced H3cit enhancement may result from clearance failures and delay degradation of CX3CR1+ macrophages in lupus." (PMID 37922035, 2023). "In inflammation and specifically lupus, the literature displays contradictory evidence for the functions of CX3CL1/CX3CR1 interactions." (PMID 38299151, 2023). "Our previous study showed that CD14+CD16+ monocytes in patients with systemic lupus erythematosus showed inflammatory phenotype, with increased CD80, CD86, HLA-DR, and CX3CR1, which could promote Th17 response." (PMID 32958023, 2020). "CX3CR1- and CD103-expressing cells are primarily APC that can capture bacteria from the gut lumen and transport them to the MLN, where they present antigens and activate CD4+ T cells to produce IL-6 that suppresses Treg, which is vital to lupus pathogenesis in lpr mice." (PMID 28697806, 2017). "Unlike MRL/lpr mice, CX3CR1 and CX3CL1 expression in the kidney of NZB/W F1 mice do not change with lupus progression, suggesting differences between various lupus-prone mouse models." (PMID 27403037, 2016). "Therefore, in the context of lupus, the absence of CX3CL1/CX3CR1 interaction may facilitate migration of Gr1+ inflammatory monocytes to the kidney, causing injury." (PMID 38299151, 2023).
pancreatic cancer (12 papers, 2012 to 2025). "Hence, HIF-1α and CX3CR1 expression is strongly associated with more PNI in pancreatic cancer patients." (PMID 22952674, 2012). "CX3CL1 exclusive receptor CX3CR1 was expressed in different tumor such as breast, liver, prostate, and pancreatic cancer." (PMID 35478937, 2022). "From the previous reports, CX3CL1/CX3CR1 axis was involved in the pathogenesis of various types of tumors, including breast, gastric, lung, colorectal, and pancreatic cancer." (PMID 35478937, 2022). "For example, previous study demonstrated that overexpression of CX3CR1 was an early event in pancreatic cancer progression and regulated tumor invasion." (PMID 35478937, 2022). "Meanwhile, overexpression of HIF-1α protein upregulated the expression of CX3CR1 in pancreatic cancer cells." (PMID 22952674, 2012). "To identify the function of HIF-1α and HIF-2α in hypoxia-induced expression of CX3CR1 in pancreatic cancer, we used three specific siRNAs targeting HIF-1α or HIF-2α and all of them effectively reduced HIF-1α or HIF-2α expression." (PMID 22952674, 2012). "In this study, we have confirmed that CX3CR1 was highly expressed in both clinical samples and cell lines of pancreatic cancer and that hypoxia induced the expression of CX3CR1." (PMID 22952674, 2012). "Although the role of CX3CR1 in the neurotropism of pancreatic cancer has been established, the regulatory mechanism of this chemotactic migration remains to be elucidated." (PMID 22952674, 2012). "Recent evidence has shown that the CX3CL1/CX3CR1 pair plays a major role in adhesion, migration and survival of tumor cells including pancreatic cancer cells." (PMID 22952674, 2012). "Overexpression of HIF-1α significantly upregulated the expression of luciferase reporter gene under the control of the CX3CR1 promoter in pancreatic cancer cells." (PMID 22952674, 2012). "Increased CX3CL1 promoted the recruitment of pancreatic tumor cells expressing CX3CR1." (PMID 35478937, 2022). "Increased CX3CL1 promoted the recruitment of CX3CR1-expressing pancreatic tumor cells." (PMID 35478937, 2022). "However, fractalkine has protumoral effects for prostate, breast, and pancreatic cancers; high expression of CX3CR1 in these cancers promotes metastasis." (PMID 28903329, 2017). "Since hypoxia is a common feature of the microenvironment of solid tumors, it is important to detect whether hypoxia promotes the expression of CX3CR1 in pancreatic cancer cells." (PMID 22952674, 2012). "Here, we report that hypoxia upregulates the expression of CX3CR1 in pancreatic cancer cells." (PMID 22952674, 2012). "This associates with an upregulated expression of the CX3CL1 receptor, CX3CR1, in pancreatic cancer specimen and therefore our array analysis prompted us to investigate whether the TRAIL-NF-κB mediated CX3CL1 expression directly affects the apoptosis resistance of PDAC cells." (PMID 29867042, 2018). "The relevance of some chemokine receptors, such as CX3CR1, CXCR4, and CXCR3, has been described in pancreatic cancer." (PMID 36142575, 2022). "In this study, we aimed to investigate (i) the mechanism of CX3CR1 regulation by hypoxia, (ii) the role of HIF/CX3CR1 in the chemotactic migration of PDAC, and (iii) the correlation between HIF and CX3CR1 in specimens of pancreatic cancer." (PMID 22952674, 2012). "The high frequency of CX3CR1 and the marked perineural invasion in PADC patients supported the concept that CX3CR1 may have an important role in the spreading of pancreatic cancer cells along peripheral nerves and in predicting early tumor relapse after surgery." (PMID 24799766, 2014). "It has been demonstrated that CX3CR1 could regulate migration and PNI of pancreatic cancer cells." (PMID 22952674, 2012).